RNU6-398P (RNA, U6 small nuclear 398, pseudogene)
Gene: Small nuclear RNA gene on chromosome 14 (60,974,327 to 60,974,435, forward strand). Ensembl gene ENSG00000206870.
Homologues: Orthologues: chimpanzee U6 (99% identical), macaque U6 (94% identical). Paralogues in human: RNU6-43P (91% identical), RNU6-11P (88% identical), RNU6-34P (88% identical), RNU6-37P (88% identical), RNU6-140P (87% identical), RNU6-19P (87% identical), RNU6-24P (87% identical), RNU6-25P (87% identical), RNU6-33P (87% identical), RNU6-698P (87% identical), RNU6-1 (86% identical), RNU6-1060P (86% identical), and 1288 more.